IL31 (interleukin 31)
Diseases named in the same sentence as IL31 in open-access papers (continued):
Sharing a sentence is not in itself a finding about the gene and the disease.
Pruritus (continued). "Recent studies have shown that IL-31 is a key determinant of pruritus in AD." (PMID 31434203, 2019). "Interestingly, mice which overexpressed IL-31 were observed to develop severe pruritus, alopecia and skin lesions." (PMID 31281316, 2019). "To determine whether apigenin has similar effects in vivo, using Compound 48/80, we developed an atopic dermatitis itch model in mice and found an increase in IL-31 expression in the skin." (PMID 30987029, 2019). "Serum IL-31 level was found to be associated with subjective sleep loss and decreased stage N1 sleep, but did not correlate significantly with pruritus severity score." (PMID 27043528, 2016). "Nevertheless increased levels of IL-31 were observed in patients with severe pruritus; therefore it might be a rationale for therapeutic approach for some patients." (PMID 27294147, 2016). "The absence of Notch-mediated downregulation of activator protein-1 results in upregulation of the levels of IL-31 and may aggravate IL-31-mediated pruritus in AD." (PMID 27483258, 2016). "The current study was undertaken to analyze whether IL-31 is also involved in the pathogenesis of pruritus in LP." (PMID 25756056, 2015). "As a result, it has also been proposed that imatinib mesylate might operate as a dose-dependent inducer of chemoattractant substances able to induce pruritus, such as IL-33 and IL-31." (PMID 26316486, 2015). "IL-31 has been shown to be one of the many mediators inducing inflammation and pruritus in atopic dermatitis and its serum level could be used as an objective reliable marker of atopic dermatitis severity in children." (PMID 25054142, 2014). "The suppression of pruritus indicator, such as IL-31, is a possible explanation for our findings." (PMID 23108364, 2013). "Recent data indicated that pruritus could be also evoked by opioid system, prostanoids, interleukin 31, serotonin, or proteases." (PMID 18288273, 2007). "Apart from the association with pruritus, IL-31 is also thought to contribute to immune evasion in HL and in CTCL: in the tumor microenvironment, high IL-31 may shift the balance from anti-tumor Th1 responses—mediated by IFNgamma—towards immunosuppressive Th2 cytokines." (PMID 38398754, 2024). "Based on the available literature, eosinophils, IgG autoantibodies, IgE autoantibodies, SP and its receptor NK1R, IL-31 and its receptor OSMRb, IL-31RA, IL-13, IL-4, periostin, and basophils may be responsible for pruritus in BP and could be potential therapeutic targets." (PMID 39459488, 2024). "Blockade of IL-31 by Lokivetmab prevents IL-31 from binding to its receptor and therefore inhibits IL-31-mediated cellular messaging, providing relief from dermatitis-related pruritus for at least 4 weeks after a single subcutaneous injection (1 mg/kg) in atopic dogs." (PMID 38932349, 2024). "Moreover, it does not inhibit IL-31-mediated pathways, such as those responsible for eyelid pruritus associated with atopic dermatitis." (PMID 39717308, 2024). "mDCs may be a major source of IL‐31 and appear to play a role in the development of pruritus in PN." (PMID 36789100, 2023). "It was found that IL-31 signaling through a heterodimeric receptor complex composed of an IL-31Rα subunit and an oncostatin M receptor β subunit (OSMRβ), expressing on the keratinocytes and the epithelial cells, induces severe dermatitis and pruritus in transgenic mice." (PMID 35324695, 2022). "Therefore, IL-31 seems to play crucial role in inducing pruritus across the species and may be dysregulated in dogs with AD16." (PMID 34075152, 2021). "In contrast to TSLP, IL-31 induced late pruritus response in humans after skin challenge, suggesting that IL-31 may exert pruritus indirectly via secondary mediators from skin cells such as keratinocytes rather than direct activation of sensory nerve receptors in the skin." (PMID 34281281, 2021). "Furthermore, IL-4, IL-13, and IL-31 stimulate sensory neurons directly, resulting in pruritus." (PMID 34200009, 2021).
Pruritus (continued). "Thus, suppressing the development of the sensory nerve density in AD and inhibiting the IL-31 pathway related to development could lead to attenuation of pruritus in AD." (PMID 33539470, 2021). "Moreover, Il31ra-deficient mice do not develop pruritus and dermatitis in response to mouse IL-31, and the administration of an anti-mouse IL-31 antibody ameliorates the scratching behavior in NC/Nga mice with atopic dermatitis-like skin lesions." (PMID 33924978, 2021). "Thus, next to the direct engagement of peripheral sensory neurons, IL-31 may sustain pruritus via keratinocyte activation and the release of other pruritus mediators." (PMID 33644104, 2021). "Association of IL-31 with its receptor alpha (IL-31Ra) on the immunological cells, keratinocytes and neural fibres results in the activation of Janus kinase and Signal Transducer and Activator of Transcription (JAK/STAT), which plays important role in the development of pruritus." (PMID 33074181, 2020). "Therefore, suppressing the expression and production of IL-31 in cellular processes will be beneficial for the treatment of chronic inflammatory diseases, including but not limited to atopic dermatitis, pruritus, inflammatory bowel diseases, and airway hypersensitivity." (PMID 30987029, 2019). "Therefore, IL-31 has been thought to be an important cytokine for regulating pruritus and AD disease activity; however, how IL-31 is involved in the immune response in AD has remained largely unknown." (PMID 31434203, 2019). "Moreover, it is probable that IL-31 may generate pruritus through the induction of a yet unknown keratinocyte-derived mediator, which subsequently activates unmyelinated C fibers in the skin." (PMID 26316486, 2015). "IL31 is aT cell cytokine associated with pruritus, and DRG neurons express the IL31 receptor Co-expression of IL31ra with Nppbsuggests that these neurons may be specialized in mediating itch." (PMID 25525749, 2014). "In addition, the decrease of its concentration during irradiations, accompanied by the decrease of pruritus, is a sign that IL-31 may play the role in pathogenesis of psoriatic pruritus." (PMID 23108364, 2013). "Meanwhile, IL-31 initiates acute pruritus by engaging IL-31Rα on TRPV1+ sensory neurons, and TGF-β promotes IL-31 production in dermal conventional type 2 dendritic cells." (PMID 41596464, 2026). "A significant correlation between IL-31 levels and disease severity markers, such as Scoring Atopic Dermatitis (SCORAD) index, and subjectively assessed pruritus intensity has been repeatedly demonstrated." (PMID 41155460, 2025). "Future studies should explore the relationship between SERPINB3/4 and other clinical parameters, such as itch mediators (e.g., IL‐31, TSLP) and neuronal activation markers, to better understand its role in pruritus." (PMID 40995892, 2025). "In vivo studies show that blocking TRPV1 disrupts IL-31 signaling, highlighting TRPV1 as a potential therapeutic target in pruritus." (PMID 41155460, 2025). "Consequently, therapeutic strategies should be tailored according to immunological phenotype: anti-IL-31 antibodies such as lokivetmab may be optimal for pruritus-dominant phenotypes, while JAK inhibitors provide broader cytokine modulation suitable for mixed or chronic inflammatory patterns." (PMID 41303472, 2025). "In lesional skin of patients with AD, MCs release a repertoire of bioactive mediators, including histamine, IL-31, tryptase, and NGF, at markedly elevated levels, reflecting an active state of the MC–neuron axis in the pathogenesis of pruritus." (PMID 41235218, 2025). "In CPG, dermal expression of IL-31, IL-31RA Oncostatin M (OSM) and periostin are well correlated with pruritus intensity." (PMID 38493053, 2024). "The secretion of histamine and interleukin (IL)-31 was examined in the human-derived mast cell line, HMC-1, and in an acute pruritus-induced animal model." (PMID 39519379, 2024).
Pruritus (continued). "Most strikingly, both IL-31 and substance P were not only significantly elevated in MF compared to healthy controls but also showed significantly higher levels in MF patients with current itch compared to those without, highlighting their strong association with pruritus in MF patient." (PMID 39068637, 2024). "The development of pruritus in canine atopic dermatitis (CAD) is induced by several endogenous mediators, one of them being Interleukin 31 (IL-31)." (PMID 38932349, 2024). "Although IL-31 appears to contribute to the induction of pruritus in PSO, its significance regarding its effect on pruritus intensity in PSO is divergent." (PMID 37834183, 2023). "In addition, H. pylori infection may reduce IL-31, thereby alleviating pruritus." (PMID 37978564, 2023). "Cytokines including IL-31, IL-4, IL-13, and TSLP are crucial for pruritus in AD transmit their signals into the cells via JAK-1 and JAK-2." (PMID 36983094, 2023). "IL-31 and its receptors IL-31RA and OSMR are involved in AD, pruritus, and dermatitis at the mRNA level." (PMID 36674561, 2023). "The significant associations that we observed between serum IL-31 levels and pruritus intensity, disease severity (UAS7), and quality of life (DLQI) underscore IL-31’s potential as a key player in the pathophysiology of CSU." (PMID 37762898, 2023). "Beside basophils, eosinophils, SP, NK1R, IL-31, IL-31RA, OSMR, IL-13, and periostin were also correlated with the severity of pruritus, and eosinophils were identified as a major source of IL-31." (PMID 37509055, 2023). "Pruritogens, including TAC1, IL-2, IL-31, TPSAB1, TPSB2, and TPSG1, and the key enzymes that are attributed to itch, including HDC and TPH1, were detected by RNA-seq." (PMID 35632808, 2022). "Pruritus severity was assessed using the Numerical Rating Scale (NRS), and the serum levels of IL-31 were measured." (PMID 35324695, 2022). "JAK/STAT-mediated production of cytokines including IL-4, IL-13, IL-31, and TSLP inhibits the expression of important skin barrier proteins and triggers pruritus in AD." (PMID 35889539, 2022). "Histamine, IL-33, IL-31, IL-4, IL-13, and thymic stromal lymphopoietin (TSLP) have been suggested to be mediators of pruritus in AD." (PMID 35163297, 2022). "IL-31 binds to IL-31 receptor (IL-31RA/OSMRβ) and activates JAK1/JAK2 and downstream STAT3 (to a lesser extent STAT1 and STAT5), then induces pruritus." (PMID 33924978, 2021). "As it was suggested that IL‐31 may evoke itch by acting on IL‐31RA‐expressing neurons, blocking IL‐31/IL‐31RA interactions has been proposed as a strategy to alleviate Th2‐mediated itch in order to allow patients to break out of the vicious circle of itching and scratching." (PMID 32648940, 2021). "Several Th2 cytokines can contribute to pruritus during scabies, including IL-4, IL-13 TSLP, IL-31, and periostin." (PMID 33807098, 2021). "IL-31, IL-4, IL-13, TSLP, and IL-5, as well as other cytokines influence inflammation and pruritus in AD." (PMID 34026782, 2021). "However, the precise details remain to be clarified, as a preclinical study has suggested that IL-31 may be associated only with pruritus, but not inflammation in contact hypersensitivity." (PMID 33644103, 2021). "Nine of 11 patients with detectable levels of IL31 presented with advanced stage disease (≥IIB) and reported complaints of (moderate to severe) pruritus." (PMID 34027133, 2021). "Certain cytokines, such as interleukin (IL-) 17, IL-33, IL-31, and thymic stromal lymphopoietin (TSLP), play an important role in the development of pruritus." (PMID 32454868, 2020). "Keratinocytes release inflammatory mediators, such as TSLP, which in turn stimulates Th2 response and promotes production of IL-13 and IL-31, and those in conjunction with nerve growth factor (NGF), and substance P represents strong pruritus mediators." (PMID 33074181, 2020).
Pruritus (continued). "Recently, IL-31 was found to be produced by malignant T cells in cutaneous T cell lymphoma (CTCL), and serum levels of IL-31 correlated to CTCL pruritus severity." (PMID 27610225, 2016). "Elevated IL-31 levels were specifically observed in psoriasis patients with pruritus, though no clear link was found between IL-31 levels and the severity of the disease or the intensity of the itch." (PMID 39859462, 2025). "Both BP and PN are classified as Th2-dominant pruritic diseases, BP—but not PN—exhibits a neuro-sensitizing immune signature (high IL-31, IgE-autoantibodies, and eosinophil-derived neurotoxins) that aligns with the NMB-associated pruritus phenotype." (PMID 41346997, 2025). "Therefore, the current study aimed to evaluate the efficacy of DHS on LPS-induced microglia activation and IL-6-and IL-31-induced astrocyte activation, and also to determine the efficacy of DHS on chloroquine-induced pruritus in mice." (PMID 40443235, 2025). "Murine-model studies have shown that IL-31 acts on transient receptor potential (TRP) family receptors to mobilize calcium influx into sensory neurons, making it a potential therapeutic target for treating T-helper-cell-dependent itch." (PMID 40142630, 2025). "The effectiveness of IL-31 blockade in non-AD-related pruritus, including hepatobiliary disorders, warrants further investigation." (PMID 40491654, 2025). "Conversely, chronic pruritus frequently involves non-histaminergic mechanisms, driven by cytokines such as interleukin-4 (IL-4), interleukin-13 (IL-13), and particularly interleukin-31 (IL-31)." (PMID 41166019, 2025). "First, patients undergoing hemodialysis who develop pruritus with no obvious visible signs of inflammation have significantly higher serum levels of C-reactive protein, IL-6, IFN-γ, IL-2, and IL-31 than patients without pruritus." (PMID 40596915, 2025). "The reduction in pruritus observed after MTX treatment may be influenced, in part, by the reduction in IL-31 gene expression." (PMID 37730501, 2024). "A comparison of MF patients with and without pruritus revealed higher levels of IL-31, substance P, GRP, and CCL24 in the former." (PMID 39068637, 2024). "The number of MRGPRX2+ cells did not correlate with disease severity, disease duration, pruritus, QoL impairment, eosinophil numbers, and serum levels of tryptase, total IgE, substance P, IL-31, eosinophilic cationic protein, and major basic protein." (PMID 38022672, 2023). "In the previous canine IL-31 pruritus studies, there were no assessments of the IL-31 effect on immediate and delayed itch responses in healthy dogs." (PMID 37235412, 2023). "A previous CSU study suggested that IL‐31 is not the primary mediator of pruritus, as some patients with high disease activity had undetectable levels of IL‐31, and the highest IL‐31 level was lower than what is required to induce itch sensation." (PMID 37632245, 2023). "Furthermore, IL-31 signaling pathway was persistently upregulated in the CTCL model and played a critical role in pruritus." (PMID 36520531, 2023). "Additionally, the expression levels of IL-31, IL-31RA and OSMRβ in skin lesions of CTCL patients have been found to be increased, and the expression levels of IL-31 correlate with pruritus intensity." (PMID 37555911, 2023). "In this study, which aimed to deepen the immune aspect of CKD-aP pathogenesis, the results showed a significant elevation of IL-31 in patients reporting CKD-aP compared to HD patients without pruritus." (PMID 35324695, 2022). "M2 macrophages have also been shown to contribute to pruritus via IL-31 in some dermatoses, but we have not found any studies linking pruritus in LS to macrophages." (PMID 36551194, 2022). "To date, in clinical practice, only the anti-IL-31 RA antibody nemolizumab reached phase III of the clinical trial in patients with atopic dermatitis, which, combined with topical agents, resulted in a greater reduction in pruritus." (PMID 35324695, 2022).
Pruritus (continued). "We aimed not only to evaluate the serum level of IL-31 in HD patients with pruritus, in HD patients without pruritus and in healthy controls, but also to correlate the serum level of IL-31 with itch severity." (PMID 35324695, 2022). "We evaluated the serum level of IL-31 in HD patients with pruritus, in HD patients without pruritus and in healthy controls, as well as its correlation to the severity of itch." (PMID 35324695, 2022). "Serum IL-31 concentrations in patients receiving maintenance hemodialysis were reported to be higher in those patients with pruritus than in those without pruritus." (PMID 35558086, 2022). "The inhibition of JAK ensures the inhibition of receptors; therefore, the subsequent biological effects, from a greater number of cytokines, are variably involved in the pathogenesis of pruritus, not only IL13 and IL4 but also IL31, IL2, IL8, IL25, IL33, IFNγ and thymic stromal lymphoprotein (TSLP)." (PMID 35890180, 2022). "The number of IL-31+CD68+ cells was shown to be significantly increased in stasis dermatitis with severe pruritus compared with that without severe pruritus." (PMID 33924978, 2021). "In patients receiving hemodialysis, individuals with uremic pruritus have significantly increased serum levels of IL-31 compared with the levels in those without pruritus." (PMID 33924978, 2021). "It has been reported that in patients receiving maintenance hemodialysis, the serum IL-31 concentration is higher in patients with pruritus than in those without pruritus." (PMID 33754202, 2021). "In line with our findings in serum, we found that transcriptional expression for IL31 in skin was not quantifiable further suggesting that alternative mechanisms are more important in the pathogenesis of pruritus in CTCL." (PMID 34027133, 2021). "For example, IL-31 mRNA was expressed in a mouse model of atopic dermatitis experiencing pruritus than in mice model of atopic dermatitis not experiencing pruritus." (PMID 30987029, 2019). "Although pruritus does often accompany cutaneous lupus erythematosus it is usually mild in severity and, possibly indicating that IL-31 is not a major player in this disease." (PMID 31281316, 2019). "In summary, we demonstrated here that IL-31 is involved in pruritus reactions without affecting induction of local skin inflammation in CHS." (PMID 29703903, 2018). "Our findings suggest that IL-31 is responsible for pruritus, but not induction of local skin inflammation, during CHS induced by FITC and DNFB." (PMID 29703903, 2018). "Using those mice, we demonstrated for the first time that IL-31 is important for induction of pruritus, but not inflammation, in CHS induced by FITC and DNFB." (PMID 29703903, 2018). "For the first time we have demonstrated that IL-31 is overexpressed in the lesional skin of LP but its expression does not correlate with intensity of pruritus." (PMID 25756056, 2015). "In addition, IL-31 is directly involved in pruritus found in AD patients as it is exhibited more in AD mice undergoing pruritus than in AD mice without pruritus." (PMID 40443235, 2025). "Additionally, IL-31, another TH2 cytokine, contributes to the characteristic pruritus seen in AD." (PMID 40566057, 2025). "The lack of difference in pruritus intensity between AD subgroups may be due to their secretion of comparable levels of IL-4, IL-22 and IL-31, as well as similar levels of tryptase." (PMID 40869144, 2025). "Pruritus often occurs in the absence of visible rash and may be mediated by IL-31, substance P, and other pruritogenic factors released by keratinocytes or sensory nerves following pathway inhibition." (PMID 41463055, 2025). "Our data indicate that non-histaminergic mediators such as tryptase and IL-31 may contribute to the pathogenesis of pruritus in MF." (PMID 39068637, 2024).